CD4 (CD4 molecule)
Diseases named in the same sentence as CD4 in open-access papers (continued):
Sharing a sentence is not in itself a finding about the gene and the disease.
malaria (continued). "Study participants also experienced marked improvement in CD4 count and haemoglobin levels following malaria treatment." (PMID 31126288, 2019). "In contrast to the findings with an increased expression of CTLA-4 and PD-1, the frequencies of GrzB+ or CD39+ CD4+ T cells were selectively increased in children with uncomplicated malaria, compared to children with complicated malaria." (PMID 29555909, 2018). "Conversely, children with uncomplicated malaria showed a higher proportion of CD4+ T cells expressing CD39 and Granzyme B, compared to children with complicated malaria." (PMID 29555909, 2018). "The highest frequencies of CTLA-4+ and PD-1+CD4+ T cells were found in children with complicated malaria, supporting prior observation with children in endemic areas and adult malaria patients." (PMID 29555909, 2018). "Deciphering the signals that shape the CD4+ T cell phenotype in malaria will be important for new treatment and immunization strategies." (PMID 29555909, 2018). "We previously showed that a chemically attenuated whole parasite asexual blood-stage vaccine induced CD4+ T cell-dependent protection against challenge with homologous and heterologous parasites in rodent models of malaria." (PMID 30293531, 2018). "Sharing of laboratory resources between HIV and non-HIV services was described as problematic due to the relatively lengthy processes involved in running HIV tests such as CD4 count tests as compared to say, tests for malaria or pregnancy screening." (PMID 30185191, 2018). "A number of studies have also explored the effect of in utero malaria exposure on cord blood immune cell populations including dendritic cells (DCs), γδ T cells, CD4+ T regulatory, and effector cells." (PMID 30384846, 2018). "In ART stable patients with CD4 counts ≥250 cells/μL, continued CPT significantly reduces risk of severe bacterial infections and protects against malaria, while discontinuing CPT reduces haematological adverse events." (PMID 30596666, 2018). "In contrast, in the asymptomatic children, it was found that fewer cells expressed both activation markers on either CD4 or CD8 T cells indicating reduced cellular activation when compared to children with symptomatic malaria." (PMID 30005684, 2018). "Studies with P. chabaudi, which causes a rapidly resolving acute parasitemia followed by multiple recrudescent bouts over many months showed that CD4+ T cells are required to control malaria by their ability to help B cells." (PMID 30631323, 2018). "In both human and murine malaria, CD4+ and CD8+ T cells are producers of IFN-γ, which have been shown to play crucial protective and pathological roles." (PMID 29892278, 2018). "The higher frequencies of PD-1+ and CTLA-4+ CD4+ T cells are therefore most likely a consequence of the very strong T cell activation in complicated malaria, which then contributes to the more severe symptoms of the patients." (PMID 29555909, 2018). "Together, our results indicate that improving CD4+ T cell activation enhances protective immunity against malaria." (PMID 30073152, 2018). "In contrast to the observation with CTLA-4 and PD-1, Tim-3 was more frequently expressed on CD4+ T cells in children with uncomplicated versus complicated malaria." (PMID 29555909, 2018). "Children with asymptomatic malaria had significantly lower levels of CD69+ expression on CD4+ T cells compared to children with symptomatic disease (P = 0.0016) but had comparable levels with the controls (P > 0.05)." (PMID 30005684, 2018). "Additional longitudinal and functional studies are urgently needed to further investigate if and how CTLA-4+PD-1+CD4+ T cells display a detrimental effect in malaria or rather prevent a worse course of disease." (PMID 29555909, 2018). "To conclude, the data presented here suggest a role for HLA genotype in RTS,S-mediated protection from malaria which is consistent with a role for both CD4+ and CD8+ T cells in protective immunity." (PMID 29439870, 2018).
malaria (continued). "T, B, and NK lymphocyte counts have been found to be reduced in severe malaria patients, whereas the percentage of activated T CD4+, NK, and γδT lymphocytes were higher in cerebral malaria patients compared to mild malaria patients." (PMID 30533319, 2018). "Children with complicated malaria had higher frequencies of CTLA-4+ or PD-1+ CD4+ T cells than children with uncomplicated malaria." (PMID 29555909, 2018). "CD4 T cells play a central role in protection of chronic infections such as malaria, LCMV and Leishmania in mice, but the protection established wanes on cure of the infection." (PMID 29630679, 2018). "Upregulation of PD-1 expression by CD4 and CD8 T cells has been associated with T cell dysfunction in the setting of chronic infections, including malaria, HIV, HCV, and HBV." (PMID 30233588, 2018). "Significantly, flow cytometric analysis and automated multivariate clustering, has revealed more frequent expression of CTLA-4 or PD-1 on CD4+ T cells from children with complicated malaria compared to uncomplicated malaria." (PMID 30631323, 2018). "The increased expression of CD39 and GrzB in children with uncomplicated malaria suggests a protective effect of CD4+ T cells expressing these markers regarding the development of malaria-associated complications." (PMID 29555909, 2018). "In this study, we have measured detectable CD4+ T cell memory response against both malaria antigens and Sh antigens and demonstrated multifunctional cellular responses against both antigens during an active malaria transmission season." (PMID 29449839, 2017). "We have recently shown that in areas of high malaria transmission, inflammatory CD4 T cells producing IFNγ and TNFα dominate in immune adults, who rarely experience high-density infections or clinical malaria despite constant exposure to infection." (PMID 29097996, 2017). "Our findings shed new light on the dynamic changes of γδ T cells and CD4+ T cells during follow-up of asymptomatic children living in an area where malaria is endemic." (PMID 28821806, 2017). "Another group of cells studied extensively in malaria, the CD4+ T cells, play a central role in immunity to malaria parasites." (PMID 28821806, 2017). "Diagnosing malaria, prompt antiretroviral therapy, monitoring CD4 count and some hematology indices on regular basis is critical." (PMID 28346490, 2017). "Anemia, increase plasma viral load and decrease CD4 count among HIV infected are some of the worse health outcomes due to frequent episodes of symptomatic malaria." (PMID 28346490, 2017). "Although recent studies have been able to characterize cytokine profiles of pediatric CD4+ T-cell populations, these have related the cytokine responses with malaria protection." (PMID 28426727, 2017). "Particularly concerning the stimulatory signaling required for optimal activation of CD4 T cells, which have a central role in protection against malaria by producing IFNγ and helping B cells to secrete antibodies." (PMID 28859168, 2017). "Here, we evaluated the role of P2X7 receptor in the CD4 T cell response during blood-stage Plasmodium chabaudi malaria." (PMID 28859168, 2017). "At the time of malaria infection, 12/24 SN children and 15/23 SP children (P = 0.29) stimulated with malaria antigens demonstrated memory recall as defined by CD4-derived cytokine production." (PMID 29449839, 2017). "Yet despite the central role of CD4 T cells in regulating protective versus deleterious immunity during malaria, their cognate antigens, as well as the antigen‐presenting cells (APC) controlling their differentiation, are poorly characterized." (PMID 28935714, 2017). "In general, to achieve better management of all HIV patients in this setting, diagnosing malaria, prompt antiretroviral therapy, monitoring CD4 and some hematology indices on regular basis is critical." (PMID 28346490, 2017).
malaria (continued). "In malaria, CD4 Th1 and T follicular helper (TFH) cells are important for controlling parasite growth, but Th1 cells also contribute to immunopathology." (PMID 28935714, 2017). "Our data suggest opposing roles for TNFα and IL10 Pf-specific CD4 T cells in naturally acquired immunity to malaria in children." (PMID 29097996, 2017). "Recent studies showed that reduced protective immunity in C5aR-/- mice was due to impaired function of malaria-specific CD4+ T-cells and consequent differentiation of effector memory (CD62LlowCD44high) and central memory (CD62LhighCD44high) CD4+ T-cells." (PMID 28426727, 2017). "It has achieved modest protection in phase III trials that correlate with anti-CSP-antibody titers and with CD4+ T cell responses—evidence that antibodies against sporozoite antigens can afford protection against malaria in humans." (PMID 29263882, 2017). "CD4 T cells have a dual role in protection against blood-stage malaria by producing IFNγ and helping B cells to secrete antibodies." (PMID 28859168, 2017). "A recent study identified a novel subset of malaria antigen-specific, IL-27-producing regulatory CD4+ T cells in mice infected with Plasmodium berghei ANKA." (PMID 28255204, 2017). "A second substantial finding is that during severe malaria, cDC1 are critical for priming and promoting parasite‐specific Th1 CD4 T cells." (PMID 28935714, 2017). "46.2% of cytokine-producing CD4+ T cells expressed a single cytokine after stimulation with malaria antigen during the malaria episode." (PMID 29449839, 2017). "Characterizing MHC II ligands and creating parasite‐specific reporter T cells are critical steps to understand the modalities of antigen presentation and CD4 T‐cell polarization during blood‐stage malaria." (PMID 28935714, 2017). "In conclusion, the implication of DC subsets in controlling endogenous CD4 T‐cell responses during severe malaria remains unsettled." (PMID 28935714, 2017). "Cytokine-producing CD4 T cells have important roles in immunity against Plasmodium falciparum (Pf) malaria." (PMID 29097996, 2017). "During the acute malaria episode, 45.7% of cytokine-secreting CD4+ T cells expressed a single cytokine after stimulation with malaria antigen with the remainder expressing more than one cytokine." (PMID 29449839, 2017). "Prior studies in both humans and animal models support an important role for CD4 T cells in mediating immunity to malaria [reviewed in Ref." (PMID 29097996, 2017). "In malaria, the respective contributions of DC subsets in controlling CD4 T‐cell activation are ill‐defined." (PMID 28935714, 2017). "All individuals exhibited a measurable CD4 T-cell response to malaria, and among cytokine-producing CD4 T cells, on average 58% were monofunctional (produced a single cytokine), 36% coproduced two cytokines, and 4% coproduced all three cytokines." (PMID 29097996, 2017). "In an environment where malaria is common, the incidence of clinical malaria episodes is reported to be higher in patients with CD4 cell counts <200 cells/μl than in those with CD4 cell counts >500 cells/μl." (PMID 28346490, 2017). "CD4 T-cell responses are important components of naturally acquired and vaccine-induced immunity to malaria [reviewed in Ref." (PMID 29097996, 2017). "We demonstrated enhanced CD4+ TEM in PBMC from Malian children who demonstrated antigen recognition of malaria proteins, which appeared predominantly in children with an inflammatory expression profile characterized by IFN-γ secretion." (PMID 29449839, 2017). "A recent report indicated that a subset of regulatory CD4+ T cells produce IL-27 in response to malaria antigen recognition during infection." (PMID 28255204, 2017). "While much of the protective immune response to malaria is thought to be due to liver tissue-resident CD8 T cells, IL-4-secreting CD4+ T cells are thought to be critical for mediating CD8 T cell response to malaria liver antigens." (PMID 29449839, 2017).
malaria (continued). "Next, we wanted to address which APC subset(s) control the generation of parasite‐specific CD4 T cells by presenting malaria antigens on MHC II." (PMID 28935714, 2017). "The findings indicate a direct association between the CD4+/CD8+ T-cells ratio and plasmatic IL-10 cytokine levels, selectively in patients with recurrent malaria." (PMID 27581163, 2016). "Pearson correlation analysis showed that the PD1 expression correlated strongly with CTLA4 expression on CD4+ T cells (r = 0.83) in malaria patients." (PMID 27802341, 2016). "Recurrent malaria patients displayed the highest plasmatic IL-10 levels, that correlated directly with the CD4+/CD8+ T-cells ratio and the number of malaria episodes." (PMID 27581163, 2016). "Both the cellular and humoral immune responses are thought to play a role in the protection against malaria, and their activity is regulated by the CD4+ T cell." (PMID 27619013, 2016). "Similar lower frequencies of P. falciparum specific CD4+ T cells were observed in Ugandan under-five children with lower prior malaria incidence compared to children with higher prior incidence." (PMID 27165269, 2016). "The analysis of activated T-cells demonstrated that both malaria groups presented significantly lower counts of CD4+CD69+ and CD8+CD69+ as compared to endemic controls." (PMID 27581163, 2016). "It is also required that further investigation should be undertaken to shed light on the association between the decreased CD4+/CD8+ T-cell ratio and the increased plasmatic IL-10 levels during recurrent malaria." (PMID 27581163, 2016). "The percentage of CTLA4+CD4+ T cell was significantly higher in patients with cerebral malaria than in patients with uncomplicated malaria." (PMID 27802341, 2016). "Surprisingly, subsequent experiments showed that the PD1+CTLA4+CD4+ Teff cells in malaria patients had an acquired extrinsic regulatory function by which they suppressed the P. falciparum-specific and polyclonal proliferation of other T cells." (PMID 27802341, 2016). "A study in HIV infected ART-naïve adults in urban Entebbe, Uganda, found that the incidence of clinical malaria increased from 57/1000 person years (pyrs) among those with CD4 counts ≥500–140/1000 person years in those with CD4 <200." (PMID 27417903, 2016). "To address these research questions, we conducted a planned sub-group analysis to examine the relationship of CD4 count with malaria in the recently completed COSTOP trial in Uganda." (PMID 27417903, 2016). "Here we explored the relationship between inflammatory type I interferons, the regulation of pathogen-specific CD4 T cell responses, and humoral immunity using models of experimental malaria and systemic virus infection." (PMID 27732671, 2016). "The large sample size and the regular collection of data on exposures (CD4 count), outcomes (clinical malaria and parasitaemia) and a variety of potential confounders made it possible to investigate the research questions in great detail." (PMID 27417903, 2016). "A stringent definition of T regulatory cells was used, defined as CD25+FoxP3+CD127lo/− CD4 T cells, and compared in utero malaria exposed and unexposed infants." (PMID 27717402, 2016). "First, the relationship between current CD4 count during follow-up and malaria among participants on placebo was examined; using random effects Poisson regression to account for repeated episodes." (PMID 27417903, 2016). "This study evaluated the impact of in utero malaria exposure on the frequency and phenotype of CD4 T regulatory cells and dendritic cells, using cord blood samples from infants born in a highly malaria-endemic region of Uganda." (PMID 27717402, 2016). "Even more surprising, we found that although PD1+ CTLA4+CD4+ T cells contained the majority of malaria-specific T cells, they showed, at the same time, cell-extrinsic suppressor activity and actively downregulated T cell proliferation." (PMID 27802341, 2016).
malaria (continued). "The effect of CD4 count on malaria incidence in HIV infected adults on antiretroviral therapy (ART) was assessed in the context of a randomized controlled trial on the effect of stopping cotrimoxazole (CTX)." (PMID 27417903, 2016). "The prevalence of malaria (p < 0.001) and malaria parasite density (p = 0.005) were observed to be progressively higher in participants with CD4+ T cell count below 200cells/μl." (PMID 27619013, 2016). "In spite of the large sample size only a small number of severe malaria episodes occurred which limited the power to detect a potential effect of CD4 count." (PMID 27417903, 2016). "Investigations from the presented longitudinal study detail the relationship of cord blood regulatory and activated CD4 T cells to in utero malaria exposure." (PMID 27717402, 2016). "CD4+ T cells of the malaria patients were significantly more likely to express PD1 and CTLA4 than CD4+ T cells of the healthy volunteers (P<0.0001)." (PMID 27802341, 2016). "We found that adoptively transferred mature splenic CD4+ YFP+ GFP+ T cells from malaria parasite-infected mice were able to migrate to and accumulate within the nonlymphoid organs of malaria parasite-infected mice and, to a much lesser extent, naive mice." (PMID 26459508, 2016). "The prevalence of malaria was progressively higher in patients with CD4+ T cell count below 200cells/μl (p < 0.001)." (PMID 27619013, 2016). "IFN-γ is considered the key effector cytokine in malaria, and cytolytic CD4+ T cells have been shown to produce high levels of IFN-γ upon in vitro stimulation." (PMID 27662621, 2016). "Previous studies in HIV-infected adults have reported an increase in malaria incidence with decreasing CD4 counts, but these studies were in individuals who were not on ART." (PMID 27417903, 2016). "But our data support results from an earlier study with children in Ghana, in which a higher percentage of CTLA4+CD4+ T cells was observed in children with severe malaria, predominantly severe anemia, than in children with uncomplicated malaria." (PMID 27802341, 2016). "Recently, a unique subpopulation of malaria-specific CD4+ T cells was revealed to produce IL-27 in response to T-cell receptor stimulation, subsequently inhibiting IL-2 production and clonal expansion of other T cells." (PMID 27867385, 2016). "Only few studies have performed functional immunophenotyping during severe human malaria, and most of them focused on specific subsets of immune cells, namely NK cells, γδT cells and CD4+ T cells." (PMID 27792766, 2016). "In summary, these data show that malaria-induced PD1+CTLA4+CD4+ T cells inhibit the proliferation of other T cells in a cell extrinsic manner." (PMID 27802341, 2016). "The IL-27-producing CD4+ T cells are forkhead box P3− CD11a+CD49d+ malaria antigen-specific CD4+ T cells, and they are distinct from IFN-γ-producing Th1 or IL-10-producing Treg cells." (PMID 27867385, 2016). "Severe malaria rates decreased with increasing CD4 counts among participants with CD4 <400, then remained fairly similar in participants with higher CD4 counts." (PMID 27417903, 2016). "Currently, the updated WHO recommendation calls for TS prophylaxis in those with a CD4 count of 350 cells/mm3 or less in areas where bacterial infection and malaria are prevalent." (PMID 27431995, 2016). "In malaria, the impact of CD4+ and CD8+ T cell responses in natural infection is partially understood." (PMID 27900319, 2016). "Data analysis confirmed that both malaria groups presented decreased absolute counts of CD4+ and CD8+ T-cells as compared to endemic controls." (PMID 27581163, 2016). "IL-10 in response to EBNA1 was also produced within the CD4+ T cell Foxp3- populations in contrast to the malaria antigen, PfSEA-1 that only stimulated IL-10 from Foxp3+ Tregs." (PMID 28033393, 2016). "Flow cytometric analysis showed a more frequent expression of CTLA4 and PD1 on CD4+ T cells of malaria patients than of healthy control subjects." (PMID 27802341, 2016).